SOX18 (SRY-box transcription factor 18)
Diseases named in the same sentence as SOX18 in open-access papers (continued):
Sharing a sentence is not in itself a finding about the gene and the disease.
tumor (continued). "In summary, SOX18 and SOX30 play divergent roles in NSCLC progression: SOX18 functions as a pro-oncogenic factor driving angiogenesis and tumor–stroma interactions, while SOX30 acts as an epigenetically silenced tumor suppressor." (PMID 41373817, 2025). "Notably, SOX18 appears to function as a central node within a transcriptional network involving MEF2C, p-STAT3, and VCAM1—particularly in the tumor vasculature and invasive front—underscoring its relevance to tumor microenvironment remodeling." (PMID 41373817, 2025). "Sox18 expression is not prevalent in the adult stage, rather the activation of Sox18 is re-activated within the endothelium stems from pathological stimuli, for example, wound healing and tumour development." (PMID 34499264, 2022). "In addition, the high expression of SOX18 promoted HCC metastasis by upregulating metastasis-related genes and was reported positively correlated with poor tumor differentiation and poor prognosis." (PMID 35465267, 2022). "When it comes to tumor tissue, SOX18 expression has not been shown in tumor cells but only in stromal cells." (PMID 33152990, 2020). "In both Cdh5 and Sox18-driven lineage tracing models, a discrete population of YFP+ lymphatic vessels could be observed by D15 within the center of the tumor." (PMID 30604758, 2019). "Usually, the expression of Sox18 and COUP-TFII is suppressed after development; however, studies have indicated that these proteins might be re-expressed by tumor cells to facilitate lymphangiogenesis and metastasis." (PMID 24286034, 2013). "The nuclear colocalized SOX18 and SREBP2 in proliferating-phase IH and regrowing IH suggest that SOX18+SREBP2+ endothelial nuclei may serve as a biomarker for the vasculogenic capacity of the tumor." (PMID 39998898, 2025). "In vitro experiments demonstrate that collagen stimulates tumor cells to express vascular endothelial growth factor A (VEGFA) and directly enhances vessel formation and endothelial cell proliferation through sex determining region Y box 18 (SOX18) upregulation." (PMID 39823457, 2025). "The results found for SOX18 could indicate a possible role for this transcription factor in the malignancy and aggressiveness of the tumor, given that it is not found in healthy skin and is found in lesser quantities in benign tumors such as actinic keratoses than in malignant tumors such as cSCC." (PMID 35956111, 2022). "Recently published bioinformatic reports of public proteomic databases have revealed downregulation of SOX18 in NSCLC, with strong negative correlation of SOX family proteins expression with tumour hypoxia." (PMID 37511076, 2023). "Recently, it become evident that the expression of SOX18 gene in tumors is not restricted simply to the endothelium of accompanying blood and lymphatic vessels, and that its role in tumor development and progression might go beyond regulation of tumor angiogenesis and lyphangiogenesis." (PMID 26588701, 2015). "Now, it becomes evident that the expression of SOX18 gene in tumors is not restricted simply to the endothelium of accompanying blood and lymphatic vessels, and that its role in tumor development and progression might go beyond regulation of tumor angiogenesis and lymphangiogenesis." (PMID 26588701, 2015). "Similarly, although transcription factor SOX18 is not required for the maintenance of the LEC phenotype in adult during physiological condition, it is reexpressed on tumor blood vessels and neolymphatics (unpublished data) suggesting a potential role in tumor-induced lymphangiogenesis." (PMID 22481918, 2012).
cancer (26 papers, 2011 to 2025). A tumor composed of atypical neoplastic, often pleomorphic cells that invade other tissues. "Previous studies have reported that SOX18 is overexpressed in various types of cancers and is associated with poor patient outcomes." (PMID 37511076, 2023). "SOX18, a transcription factor upregulated in different types of cancers, and its upregulation is associated with poor prognosis via a role in angiogenesis and metastasis." (PMID 34830961, 2021). "The up‐regulation of SOX2, SOX4, SOX5, SOX8, SOX9 and SOX18 are found to be associated with poor outcome in different cancer types; however, the up‐regulation of SOX11 and SOX30 is favourable for the prognosis in other cancer types." (PMID 32363730, 2020). "More recently, high levels of SOX18 have been associated with poor prognosis for cancer in human patients." (PMID 28137359, 2017). "However, Sox18 is also associated with cancer: in particular, the results of experiments on a mouse model of skin cancer suggest that it promotes a number of processes that help cancers to spread." (PMID 28137360, 2017). "SOX18‐induced modulation of endothelial barrier integrity is crucial for cancer progression and metastasis." (PMID 39231761, 2025). "The transcription factor SOX18 plays a crucial role in both lymphatic endothelial cell differentiation and cancer‐induced lymphangiogenesis." (PMID 39791369, 2025). "To this end, we transduced a lentivirus expressing BirA*-fusion of SOX18 into KSHV-infected cancer cells (iSLK.219; and uninfected, parental (SLK) cells to differentiate interactions specific for KSHV-infection." (PMID 40894008, 2025). "SOX18 is a profound oncogene in many cancers, and FGF19/FGFR4 was found to upregulate SOX18 potentially through an interplay with Wnt signaling, specifically through the p-FRS2/p-GSK3β/β-catenin axis." (PMID 39796710, 2024). "Despite these findings, the biological responses dependent on SOX18 are highly influenced by the specific type of cancer." (PMID 37511076, 2023). "In light of these findings, SOX18 appears to be an attractive molecular target for cancer research in studies aimed at treatment or molecular-based mechanistic investigations." (PMID 37511076, 2023). "SOX18 has been studied for its role in cell cycle control, but results vary depending on the cancer type." (PMID 37511076, 2023). "It is noteworthy that there was a surge in the cytotoxicity of Sm4 in both cancer cell lines after 48 h, indicating that the inhibition of SOX18 activity, which affected cell function, required more than 24 h to take effect." (PMID 37511076, 2023). "Our results confirm significant Sm4-mediated p21 upregulation in both cancer cell lines, suggesting that modulation of SOX18 activity affects p21 expression and activity." (PMID 37511076, 2023). "The SOXF family (SOX7, SOX17 and SOX18) plays a crucial role in angiogenesis or lymphangiogenesis, and SOX18 has been shown to be a potential target for antiangiogenic therapy in cancer." (PMID 32363730, 2020). "Pharmacological inhibition of SOX18 protein function therefore presents a potential avenue for management of the vascular response in cancer." (PMID 28137359, 2017). "We have shown that SMO inhibitor cyclopamine and GLI inhibitor GANT61 are both able to down regulate SOX18 expression in HeLa cells, opening a new field of potential manipulation with this gene expression in cancer." (PMID 26588701, 2015). "Importantly, the SOXF proteins, namely SOX7, SOX17 and SOX18, were validated to play important roles in cell fate determination and multiple cancer types." (PMID 40778650, 2025).
cancer (continued). "Furthermore, growing interest and published data have led to discoveries that SOX18 is involved in the cascades of the most important molecular pathways, such as Wnt/b-catenin, mTOR, or Notch1 signalling, regulating the majority of cancer-related processes." (PMID 37511076, 2023). "Previous studies indicated that SOX18 exhibited oncogenic activity in various types of cancers." (PMID 31189744, 2019). "It is important to point out that HH signaling is mainly inactive in normal adult cells, and becomes reactivated in several cancers, so using HH inhibitors could assure selective approach in modulating SOX18 level." (PMID 26588701, 2015). "On the other hand, we detected that SOX18 transcription factor could play important role in migration of cancer cells in vitro." (PMID 26588701, 2015). "Recent studies have demonstrated that SOX18 is highly expressed in various types of cancer." (PMID 26151573, 2015). "Also, we present data that will help in understandingof SOX18’s role in the regulation of tumorigenic features of cancer cells in vitro, in particular in regulation of cancer cell’s migration and invasion, as an important step in metastatic spreading." (PMID 26588701, 2015). "Drugs that inhibit Sox18 could, therefore, help in the treatment of cancer." (PMID 28137360, 2017). "Therefore, SOX18 is a potential target for antiangiogenic therapy of human cancers." (PMID 21211035, 2011). "Further research is required to elucidate how SOX18 impacts the ESC-like cells in IH, and other VAs, cancer and fibroproliferative conditions." (PMID 35574555, 2022). "Moreover, emerging data suggest a context-dependent crosstalk between SOX18 and the STAT3 signaling pathway, a key regulator of cancer cell survival, proliferation, and immune evasion." (PMID 41373817, 2025). "Interestingly, a recent study reported that MCAM was transcriptionally activated by SOX18, a subset of SOX17 interactome, which was indispensable in cancer metastasis." (PMID 40778650, 2025). "In the case of SOX18, the observed discrepancies between mRNA and protein levels in NSCLC suggest regulation by miRNAs—specifically hsa-miR-7a and hsa-miR-24-3p—a mechanism also seen in other types of cancer." (PMID 41373817, 2025). "Additionally, resume of MCAM expression reversed the inhibitory effects of SOX18‐downregulation on cancer metastasis, whereas downregulation of MCAM abrogated the enhanced metastatic capacity in SOX18‐overexpressing cancer cells." (PMID 40778650, 2025). "In contrast, SOX18 demonstrated reduced mRNA expression in LSCC and LUAD relative to NMLT (both p < 0.0001), while its protein levels were significantly elevated in both cancer types (p < 0.0001)." (PMID 41373817, 2025). "SOX18 has emerged as a potential novel target in NSCLC due to its involvement in neoangiogenesis and modulation of endothelial barrier integrity, which are important in cancer progression." (PMID 37511076, 2023).
infection (2 papers, 2023 to 2025). The state of being infected such as from the introduction of a foreign agent such as serum, vaccine, antigenic substance or organism. "With the understanding that KSHV infection increases chromatin accessibility and SOX18 inhibition reduces chromatin accessibility in uninfected LECs, we next assessed if the increased chromatin accessibility upon KSHV-infection is SOX18-dependent." (PMID 40894008, 2025). "Infection of LECs with ΔORF50 was first validated to induce the typical SOX18-dependent infection phenotypes as rKSHV.219 and confirming that the SOX18 upregulation and its critical functions occur during latency." (PMID 40894008, 2025). "The identification of a pioneer function for SOX18 in LECs prompted us to perform an ATAC-seq upon infection to investigate whether this role might be specifically hijacked by KSHV, as de novo infection increases SOX18 protein levels in LECs." (PMID 40894008, 2025). "Therefore, we investigated here whether KSHV-infected lymphatic ECFCs engrafted into NSG mice could serve as a physiologically relevant infection model to test the potential of SOX18 inhibition as a therapeutic modality for KS." (PMID 36689549, 2023). "Upon infection, LANA co-opts SOX18 to recruit the SWI/SNF chromatin-remodeling complex via its ATPase subunit BRG1, enhancing chromatin accessibility and enabling efficient viral genome persistence." (PMID 40894008, 2025).
vascular disorder (1 paper, 2019). A general term used to describe any disease affecting blood vessels]. "Although SOX18 is involved in a variety of patho-physiological processes, HLTRS is a rare and severe vascular disorder." (PMID 31358114, 2019).
SOX18 also shares sentences with these, for which no sentence is quoted: Telangiectasia (5 papers); Distichiasis (3); blood disorders (2); cardiac diseases (2); lung adenocarcinoma (2); lymphedema-distichiasis syndrome (2); pulmonary arterial hypertension (2); abdominal aortic aneurysm (1); acute myeloid leukemia (1); adenocarcinoma (1); alcohol addiction (1); benign tumors (1); cardiomyopathy (1); chronic kidney disease (1); chronic lymphocytic leukemia (1); Chylothorax (1); Cognitive impairment (1); colorectal cancer (1); congenital hemangioma (1); Cutis marmorata (1); genetic disorder (1); hydrocele (1); Kaposi's sarcoma (1); Lung Fibrosis (1); lung squamous-cell carcinoma (1); lymphangiectasia (1); Lymphatic Metastasis (1); metastatic cancer (1); microcephaly (1); Milroy disease (1).
A further 8 diseases each share a sentence with SOX18 in 1 paper.